USP2 (ubiquitin specific peptidase 2)
Description:
Hydrolase that deubiquitinates polyubiquitinated target proteins such as MDM2, MDM4 and CCND1. Isoform 1 and isoform 4 possess both ubiquitin-specific peptidase and isopeptidase activities (By similarity). Prevents MDM2-mediated degradation of MDM4. Plays a role in the G1/S cell-cycle progression in normal and cancer cells. Regulates the circadian clock by modulating its intrinsic circadian rhythm and its capacity to respond to external cues (By similarity). Associates with clock proteins and deubiquitinates core clock component PER1 but does not affect its overall stability (By similarity). Regulates the nucleocytoplasmic shuttling and nuclear retention of PER1 and its repressive role on the clock transcription factors CLOCK and BMAL1 (By similarity). Plays a role in the regulation of myogenic differentiation of embryonic muscle cells (By similarity). [Isoform 4]: Circadian clock output effector that regulates Ca(2+) absorption in the small intestine. Probably functions by regulating protein levels of the membrane scaffold protein NHERF4 in a rhythmic manner, and is therefore likely to control Ca(2+) membrane permeability mediated by the Ca(2+) channel TRPV6 in the intestine.
Synonyms: UBP41; USP9
Tractability: Small molecule: a structure with a bound ligand is known; it belongs to a druggable protein family. Antibody: UniProt places it where antibodies can reach, with high confidence. PROTAC: a small molecule that binds it is known.
Target class: Cysteine protease; Cysteine protease CA clan; Protease; Enzyme; Cysteine protease C19 family
Gene: Protein-coding gene on chromosome 11 (119,355,215 to 119,381,711, reverse strand). Ensembl gene ENSG00000036672.
Subcellular location: Cytoplasm; Cytoplasm, perinuclear region; Nucleus (Isoform 4); Membrane
Subcellular location (Human Protein Atlas): Cytosol; Plasma membrane
Pathways (Reactome):
Signal Transduction: Regulation of TNFR1 signaling; TNFR1-induced NF-kappa-B signaling pathway; TNFR1-induced proapoptotic signaling
Metabolism of proteins: Ub-specific processing proteases
Gene Ontology:
Molecular function: cyclin binding; cysteine-type deubiquitinase activity; protein binding; ubiquitin protein ligase binding; cysteine-type endopeptidase activity; cysteine-type peptidase activity; identical protein binding
Biological process: negative regulation of transcription by RNA polymerase II; positive regulation of mitotic cell cycle; protein deubiquitination; protein stabilization; circadian behavior; circadian regulation of gene expression; entrainment of circadian clock by photoperiod; locomotor rhythm
Cellular component: cytosol; cytoplasm; membrane; nucleoplasm; nucleus; centrosome; perinuclear region of cytoplasm
Genetic constraint (gnomAD): Loss-of-function variants: 33 observed, 70.78 expected, observed/expected ratio (o/e) 0.47, 90% interval 0.35 to 0.62. The upper end of that interval is the gene's LOEUF score, 0.62, which puts it in group 2 of 6, group 1 being the genes least tolerant of losing a copy. Missense variants: 691 observed, 806.79 expected, observed/expected ratio (o/e) 0.86, 90% interval 0.8 to 0.91. Synonymous variants: 296 observed, 314.66 expected, observed/expected ratio (o/e) 0.94, 90% interval 0.86 to 1.04.
Homologues: Orthologues: chimpanzee USP2 (99% identical), macaque USP2 (93% identical), dog USP2 (93% identical), pig USP2 (92% identical), rabbit USP2 (92% identical), rat Usp2 (91% identical), mouse Usp2 (90% identical), guinea pig USP2 (89% identical), zebrafish usp2a (46% identical), Caenorhabditis elegans usp-4 (32% identical). Paralogues in human: USP21 (37% identical), USP19 (30% identical), USP4 (28% identical), USP32 (27% identical), USP15 (27% identical), USP8 (26% identical), USP11 (26% identical), USP31 (25% identical), USP9X (24% identical), USP43 (24% identical), USP6 (23% identical), USP9Y (23% identical), and 59 more.
Diseases named in the same sentence as USP2 in open-access papers:
USP2 is named in the same sentence as 85 diseases in open-access papers, as found by Europe PMC text mining. Sharing a sentence is not in itself a finding about the gene and the disease. The quoted sentences say what the papers report.
breast cancer (13 papers, 2008 to 2024). A primary or metastatic malignant neoplasm involving the breast. "Another study also suggested that in ErbB2-positive breast cancer, combinative treatment of USP2 inhibitor and Erb2 inhibitor HSP90 demonstrated synergistic therapeutic efficacy." (PMID 36567903, 2022). "Intriguingly, in contrast with our findings, prior research based on breast cancer tissues and cell line models indicated overexpression of USP2 in metastatic tumor tissues." (PMID 36567903, 2022). "USP2 expression levels in breast cancer, cervical cancer, glioma, and prostate cancer tissue are significantly higher than those in the corresponding paracancer tissue." (PMID 33619866, 2021). "Taking advantage of the successful development of the USP2 inhibitor ML364, we investigated the influence of pharmacological USP2 inhibition on ErbB2 expression in breast cancer cells." (PMID 32327714, 2020). "Taken together, our findings unveil USP2 as a guardian of ErbB2 abundance in ErbB2-positive breast cancers, with its DUB activity required to antagonize the endocytic degradation of ErbB2 under steady state conditions." (PMID 32327714, 2020). "It hence implies that the USP2 inhibitor ML364 is capable of potentiating a wide range of HSP90 inhibitors to suppress ErbB2 levels in breast cancer cells." (PMID 32327714, 2020). "ML364 is an inhibitor of ubiquitin specific peptidase 2 (USP2) in human breast cancer." (PMID 36619997, 2022). "USP2 is a circadian rhythm-related gene that is involved in multiple biological processes, such as pressure overload-induced cardiac remodeling, breast cancer, hemophilia, and energy metabolism." (PMID 36172047, 2022). "Additionally, triple-negative breast cancer, which is the most aggressive type of breast cancer, exhibits high levels of USP2 expression in conjunction with enhanced cell migration and invasion." (PMID 33530560, 2021). "Nevertheless, the information from our clinicopathological analysis suggests that USP2 could be used as a new predictive biomarker for breast cancer metastasis." (PMID 30918246, 2019). "Having observed the potentiating effects of USP2 inhibition toward 17-AAG-induced ErbB2 downregulation, we reasoned that the USP2 inhibitor ML364 might sensitize ErbB2-positive breast cancer cells to HSP90 inhibition and accordingly investigated the effectiveness of the combined treatment." (PMID 32327714, 2020). "Another recent study explored the cuproptosis-related prognostic 2-lncRNAs (USP2- AS1, NIFK-AS1) signature (BCCuS) in breast cancer and validated it as an independent prognostic factor for breast cancer." (PMID 39867656, 2024). "Depletion and pharmacological suppression of USP2 effectively enhance HSP90 inhibitor-incurred ErbB2 downregulation, as well as significantly deter the in vivo and in vitro growth of ErbB2-positive breast cancer cells." (PMID 32327714, 2020). "Next we sought to evaluate the combination of USP2 and HSP90 inhibitors using ErbB2-positive breast cancer xenograft mouse models." (PMID 32327714, 2020). "The combination of USP2 and HSP90 inhibitors effectively restrains ErbB2-positive breast cancer xenograft growth in vivo." (PMID 32327714, 2020).
breast cancer (continued). "Based on findings from the present investigation, we propose a novel therapeutic strategy to treat ErbB2-positive breast cancer via combined pharmacological inhibition of HSP90 and USP2." (PMID 32327714, 2020). "In MCF-10A mammary epithelial cells treated with adiponectin, we also found a significant increase of USP2 mRNA levels, but a decrease in MCF-7 breast cancer cells." (PMID 18827813, 2008). "We used the TCGA database to analyze the expression of USP family members, and found that USP2, USP6, USP44 and USP53 in breast cancer tissues were significantly down-regulated compared with those in normal breast tissues, among which the first three have been studied in this field." (PMID 39044157, 2024). "Importantly, the combinatorial scheme incorporating both USP2 and HSP90 inhibitors most potently repressed the further in vivo expansion of the HCC1954 breast cancer xenografts, which was evidenced by markedly attenuated tumor volumes and weights." (PMID 32327714, 2020). "As expected from our microarray data, adiponectin did not trigger elevated transcript levels of TR2, CASP1 and USP2 in MCF-7 breast cancer cells, but a significantly reduced USP2 expression by approximately 60%." (PMID 18827813, 2008).
prostate carcinoma (13 papers, 2007 to 2024). A carcinoma that arises from epithelial cells of the prostate gland. "Hence, unsurprisingly, the dysregulation of USP2 levels was associated with the development of various kinds of cancers, such as colorectal cancer, prostate cancer and oral squamous cell carcinoma." (PMID 33621249, 2021). "To date, various types of malignant tumors, including prostate cancer, hepatoma, bladder carcinoma, and glioma, have been reported to express high levels of USP2." (PMID 33530560, 2021). "The ortho-quinone natural product β-lapachone, which has been subjected to phase II clinical trials for cancer therapy, was shown to target USP2, resulting in induction of apoptosis in the DU-145 prostate cancer cell line." (PMID 33530560, 2021). "In various cancers, including prostate cancer and ovarian carcinoma, upregulation of USP2 leads to an increase in the levels of deubiquitinated substrates such as fatty acid synthase, MDM2, cyclin D1 and Aurora-A." (PMID 29449607, 2018). "It has been reported that USP2 can regulate and stabilize fatty acid synthase, an aberrantly over-expressed protein in biologically-aggressive prostate cancer cells." (PMID 30319415, 2018). "The deubiquitinating enzyme USP2 has been found to enhance MYC levels through the modulation of specific subsets of microRNAs in prostate cancer." (PMID 29511348, 2018). "In ovarian and prostate carcinoma, USP2 protein is upregulated, whereas in colon cancer, USP2 expression is downregulated." (PMID 28031783, 2016). "Mutations in the CYLD deubiquitinating enzyme leads to familial cylindromatosis and overexpression of USP2 has been reported to increase prostate cancer cell proliferation through the stabilization of fatty acid synthase." (PMID 21264218, 2011). "USP2 exhibits oncogenic potential in prostate cancer by stabilizing its substrate Fatty Acid Synthase (FAS), and FAS has indeed been identified as a target of ISG15 modification." (PMID 17653289, 2007). "Given that USP2 is upregulated by androgen, USP2 may therefore promote the onset of androgen-sensitive prostate cancer via the accumulation of ACDase." (PMID 33530560, 2021). "Among these, USP2 interacts with FASN and promotes its protein stability by reducing the ubiquitination level of FASN in prostate cancer." (PMID 39489738, 2024). "In 2004, Graner and colleagues showed that USP2 binds to and stabilizes FAS, a protein known to be upregulated in many cancers including prostate cancer." (PMID 33621249, 2021).
leukemia (6 papers, 2018 to 2022). A malignant (clonal) hematologic disorder, involving hematopoietic stem cells and characterized by the presence of primitive or atypical myeloid or lymphoid cells in the bone marrow and the blood. "Also, other deubiquitinases, such as USP2, USP8, USP10 and USP42, fuse with leukemia-associated genes, indicating that deubiquitinases play an important role in the pathogenesis of AML." (PMID 34454635, 2021). "Here a leukemia drug, 6-thioguanine, was found to be a potent inhibitor of USP2." (PMID 29449607, 2018). "Targeting USP2/USP8 may be important to improve the outcomes of MLL-rearranged leukemia." (PMID 34454635, 2021). "Until now, USP2, USP8, and USP10 have been found to be fused with MLL, which indicates that DUBs may be potential targets of MLL-r leukemia." (PMID 34454635, 2021). "Moreover, a popular leukemia drug, 6-thioguanine, was shown to be a noncompetitive inhibitor for human USP2." (PMID 33530560, 2021).
colon cancer (5 papers, 2016 to 2026). "It has been demonstrated that overexpression of USP2 inhibited TLR/IL-1β-induced NF-κB activation through deubiquitination of tumor necrosis factor receptor-associated factor 6 (TRAF6) in human colon cancer cells." (PMID 32963492, 2020). "SAB can directly bind to ubiquitin-carboxy-terminal hydrolase 2 (USP2) in colon cancer cell RKO, inhibit its deubiquitination activity, enhance the killing activity of T cells in tumor cells, and finally play an anti-tumor role." (PMID 38398656, 2024).
diabetes (5 papers, 2015 to 2026). "In hepatocytes, USP2 increases blood glucose levels via gluconeogenesis, which suggests that it plays a pathogenic role in the progression of diabetes mellitus." (PMID 36834633, 2023). "The largest change caused by diabetes occurred in Usp2 gene." (PMID 25905778, 2015). "Meanwhile, a long isoform of USP2 in adipose tissue macrophages, USP2a, attenuates the onset of diabetes." (PMID 42072324, 2026). "In addition to regulating diabetes, USP2 isoforms potentially regulate the progression of atherosclerosis by modulating macrophages and hepatocytes." (PMID 42072324, 2026). "Given this, USP2-dependent mitochondrial defects in myoblasts are likely to become more apparent in the skeletal muscle of individuals suffering from oxidative stress, such as diabetes mellitus patients." (PMID 39596006, 2024). "To confirm this, we then analyzed several known clock-controlled genes for the retina (Adcy1, Drd4, Nr2e3, Cys1, Plekbh1, Usp2) that also showed amplitude changes but no phase changes, indicating that the retinal clock was entrained to the 12L:12D cycle at this stage of diabetes." (PMID 38039846, 2024).
cardiac hypertrophy (4 papers, 2020 to 2024). "It is inferred that the beneficial effect of Mycn on cardiac hypertrophy depends on the transcriptional activation of USP2." (PMID 38297207, 2024). "Overexpression of USP2 has been found to protect the heart from pressure overload-induced cardiac remodeling, cardiac hypertrophy, inflammation, and oxidative stress in a mouse model induced by transverse aortic constriction." (PMID 38297207, 2024). "USP2 has recently been demonstrated to exert a myocardium-protective role in cardiac hypertrophy." (PMID 38297207, 2024). "This study demonstrates that Mycn activates USP2 transcription, which mediates ubiquitination and protein stabilization of JUP, thus inactivating the Akt/β-catenin axis and alleviating cardiac hypertrophy-induced heart failure." (PMID 38297207, 2024). "Lentiviral vector-carried OE-USP2 was administrated into mice, followed by ISO injection, to analyze the function of USP2 in cardiac hypertrophy." (PMID 38297207, 2024). "Overexpression of cardiac USP2 inhibited TAC-induced cardiac remodeling, by suppressing cardiac hypertrophy, inhibiting inflammatory responses and fibrosis, and attenuating oxidative stress." (PMID 32963492, 2020). "We hypothesized that USP2 possibly mediates JUP deubiquitination and inactivates the Akt/β-catenin cascade to ameliorate cardiac hypertrophy." (PMID 38297207, 2024). "Collectively, we hypothesized that Mycn possibly regulates USP2 transcription, which modulates JUP protein stability and the Akt/β-catenin signaling to affect cardiac hypertrophy progression." (PMID 38297207, 2024).
glioma (4 papers, 2021 to 2024). A benign or malignant brain and spinal cord tumor that arises from glial cells (astrocytes, oligodendrocytes, ependymal cells). "Additionally, USP2 directly stabilizes MDM4 in the cytoplasm of gliomas." (PMID 33530560, 2021). "In addition, USP2 and FASN expression levels were elevated with higher tumor malignancy in gliomas, according to the WHO classification." (PMID 39489738, 2024).
atherosclerosis (3 papers, 2021 to 2026). A disease characterized by the build-up of fatty material and calcium deposition in the arterial wall resulting in partial or complete occlusion of the arterial lumen. "USP17 increases the risk of atherosclerosis by promoting the accumulation of oxidative stress, whereas USP2 and 9X hinder the progression of disease by modulating cholesterol uptake in the liver and macrophages." (PMID 36834633, 2023). "Since blood LDL levels are a prerequisite for atherogenesis, USP2 seems to act as a protective enzyme against atherosclerosis." (PMID 36834633, 2023). "Thus, aberrant expression of USP2 is considered to provoke metabolic diseases, such as type 2 diabetes and atherosclerosis." (PMID 33530560, 2021).
colorectal cancer (3 papers, 2021 to 2024). A primary or metastatic malignant neoplasm that affects the colon or rectum. "High USP2 expression in colorectal cancer is associated with reduced antitumor immunity and poor clinical outcomes, highlighting the USP2’s negative regulatory role in T-cell immunity." (PMID 38474186, 2024).
Glucose intolerance (3 papers, 2021 to 2024). Glucose intolerance (GI) can be defined as dysglycemia that comprises both prediabetes and diabetes. "USP2 is a regulator of hepatic gluconeogenesis, and therefore overexpression of USP2 amplified lipid accumulation, glucose intolerance, and metabolic inflammation, while reducing its expression mitigated fructose-induced effects." (PMID 39796579, 2024). "Enhanced USP2 expression boosts glucose production and aggravates glucose intolerance in obese mice." (PMID 38993560, 2024). "Given that USP2-4 positively regulates the expression of several glucocorticoid-regulated genes in the liver, USP2 appears to exacerbate glucose intolerance by stimulating glucocorticoid signaling." (PMID 33530560, 2021).